MTF1 (metal regulatory transcription factor 1)
Diseases named in the same sentence as MTF1 in open-access papers (continued):
Sharing a sentence is not in itself a finding about the gene and the disease.
Hepatic fibrosis (2 papers, 2023 to 2024). The presence of excessive fibrous connective tissue in the liver. "Our results suggest that the ZnCl2 treatment ameliorates liver fibrosis by elevating intracellular zinc levels through MTF1-mediated regulation of ZIP14 expression and the reduction of ZIP14 deacetylation via HDAC4." (PMID 38221603, 2024). "Saffronin ameliorates liver fibrosis by inhibiting HSC activation via the lnc-LFAR1/MTF-1/GDNF axis." (PMID 37409114, 2023). "Significantly, we have provided novel evidence, for the first time in the literature, elucidating that MTF-1 exerts control over ZIP14 expression in conjunction with histone deacetylase activity following zinc supplementation in hepatocytes afflicted with hepatic fibrosis." (PMID 38221603, 2024). "Collectively, these findings highlight the complex interplay between MTF-1, epigenetic regulators, and ZIP14 in the context of liver fibrosis and zinc supplementation." (PMID 38221603, 2024). "The restoration of intracellular zinc concentrations and the modulation of ZIP14 expression by zinc orchestrated through MTF1 and HDAC4, appear to be essential determinants of the therapeutic response in hepatic fibrosis." (PMID 38221603, 2024).
kidney cancer (2 papers, 2022 to 2023). Primary or metastatic malignant neoplasm involving the kidney. "Similarly, we confirmed the down-regulated MTF1 expression in adrenocortical carcinoma, colon cancer and kidney cancer." (PMID 37380924, 2023).
lymphoma (2 papers, 2019 to 2022). A malignant (clonal) proliferation of B- lymphocytes or T- lymphocytes which involves the lymph nodes, bone marrow and/or extranodal sites. "Metal-responsive transcription factor-1 (MTF1) is a candidate susceptibility gene for lymphoma." (PMID 36713586, 2022).
ovarian epithelial tumor (2 papers, 2023 to 2024). A benign, borderline, or malignant tumor that originates from the surface epithelium of the ovary. "As shown in the results, the frequency of MTF1 alteration was the highest in ovarian epithelial tumors at a rate of 7.02%, which also had the highest frequency of amplification (6.68%)." (PMID 39308676, 2024). "And the histogram showed that the amplification frequency of MTF1 was the highest in ovarian epithelial tumor." (PMID 37380924, 2023).
paraganglioma (2 papers, 2023 to 2024). A benign or malignant neoplasm arising from paraganglia located along the sympathetic or parasympathetic nerves. "The results indicated that the expression of MTF1 in BLCA, BRCA, KIRC, LIHC, OV, pheochromocytoma and paraganglioma (PCPG), READ, PRAD, SKCM, and STAD showed significant differences among different immune subtypes (P < 0.05)." (PMID 39308676, 2024).
prostate adenocarcinoma (2 papers, 2023 to 2024). "As for the primary therapy outcome, complete response (CR) patients had lower MTF1 expression than non-CR patients in BLCA, DLBC, and LGG, while in HNSC and prostate adenocarcinoma (PRAD), the results were reversed." (PMID 39308676, 2024).
rectum adenocarcinoma (2 papers, 2023 to 2024). An adenocarcinoma arising from the rectum. "According to the results, patients with a higher expression of MTF1 had a shorter OS in LGG (hazard ratio (HR) = 1.85, P = 0.001) and a longer OS in HNSC (HR = 0.75, P = 0.04), KIRC (HR = 0.59, P = 0.001), and rectum adenocarcinoma (READ) (HR = 0.42, P = 0.045)." (PMID 39308676, 2024).
Stroke (2 papers, 2021 to 2024). Sudden impairment of blood flow to a part of the brain due to occlusion or rupture of an artery to the brain. "In a murine stroke model using transient middle cerebral artery occlusion (tMCAO), NCX1 protein levels decreased by ∼50%, and Mtf1 expression was significantly reduced." (PMID 39375833, 2024). "This suggests a connection between Mtf1 and NCX1 during ischemic insult, which could be targeted to mitigate stroke damage." (PMID 39375833, 2024).
uveal melanoma (2 papers, 2023 to 2024). A melanoma derived from melanocytes of the uveal tract. "At the same time, MTF1 expression in uveal melanoma (UM) was strongly negatively related to apoptosis, DNA damage and DNA repair." (PMID 37380924, 2023). "Further analyses revealed that methylation level was significantly negatively correlated with MTF1 expression in DLBC, READ, and TGCT, while positively correlated with MTF1 expression in PRAD and uveal melanoma (UVM) (|correlation| > 0.3 and FDR < 0.05)." (PMID 39308676, 2024).
acute tonsillitis (1 paper, 2025). An acute inflammation of the tonsils caused by viruses or bacteria. "Additionally, the following genes were linked to specific traits (PFDR < 0.05): MTF1: acute tonsillitis and secondary malignancy of respiratory organs." (PMID 40149491, 2025).
Anxiety (1 paper, 2025). Intense feelings of nervousness, tension, or panic often arise in response to interpersonal stresses. "MTF1 has also been shown to activate CaV3.2 expression in the early phase of epileptogenesis and in social stress-induced anxiety." (PMID 41389090, 2025).
ataxia telangiectasia (1 paper, 2021). Ataxia-telangiectasia is the association of severe combined immunodeficiency (affecting mainly the humoral immune response) with progressive cerebellar ataxia. "Recently, it has been demonstrated that the DNA damage response serine/threonine kinase ATM (mutated in ataxia–telangiectasia) increases FPN expression by enhancing the nuclear translocation of metal-regulatory transcription factor 1 (MTF1), which was previously found to trigger FPN expression." (PMID 33804198, 2021).
B-cell lymphoma (1 paper, 2023). "Increased expression of MTF1 could lead to cell cycle arrest and apoptotic responses of B-cell lymphoma lines." (PMID 37152283, 2023).
bipolar disorder (1 paper, 2010). A disorder of the brain that causes unusual shifts in mood, energy, activity levels and the ability to carry out day-to-day tasks. "MTF1 binds to the metal responsive element, which is regulated by lithium salts in the treatment of bipolar disorder and may also interact with cytosolic calcium." (PMID 20808825, 2010).
cervical squamous cell carcinoma (1 paper, 2023). A squamous cell carcinoma arising from the cervical epithelium. "We found that the cervical squamous cell carcinoma (CSCC) patients with MTF1 genetic alteration displayed a poor prognosis in DFS (p = 1.405e-3), but not DSS (p = 0.474), OS (p = 0.793) and PFS (p = 0.155)." (PMID 37380924, 2023).
channelopathies (1 paper, 2024). "An increase in MTF1 (metal regulatory transcription factor 1) was associated with the increased excitability of neurons in acquired epilepsy by the altered expression of channels (channelopathies;)." (PMID 38927072, 2024).
cholangiocarcinoma (1 paper, 2023). A carcinoma that arises from the intrahepatic biliary tree (intrahepatic cholangiocarcinoma) or from the junction, or adjacent to the junction, of the right and left hepatic ducts (hilar cholangiocarcinoma). "In contrary, MTF1 displayed higher expression in cholangiocarcinoma (CHOL) and LIHC than the corresponding normal tissues." (PMID 37380924, 2023).
Cognitive impairment (1 paper, 2025). Abnormal cognition is characterized by deficits in thinking, reasoning, or remembering. "MTF-1 was identified as a key transcription factor that plays an important role in the pathogenesis of cognitive impairment induced by 1,2-diacetylbenzene." (PMID 40560886, 2025).
colon adenocarcinoma (1 paper, 2024). "The result showed that the expression of MTF1 was significantly higher in CHOL and LIHC while lower in BRCA, colon adenocarcinoma (COAD), KICH, KIRC, KIRP, LUAD, and THCA." (PMID 39308676, 2024).
fibrosis (1 paper, 2024). the formation of excess fibrous connective tissue in an organ or tissue in a reparative or reactive process. "In our investigation, we confirmed the presence of MRE sequences on the promoter of the ZIP14 gene, and intriguingly, our results demonstrated that MTF-1 regulates ZIP14 when zinc supplementation is administered in the fibrosis groups." (PMID 38221603, 2024). "Our investigation confirmed the existence of metal-responsive element (MRE) sequences on the ZIP14 gene promoter, and notably, our results indicate that MTF-1 regulates ZIP14 when zinc supplementation is applied to the fibrosis groups." (PMID 38221603, 2024). "Our chromatin immunoprecipitation (ChIP) analyses demonstrated a clear binding of MTF-1 to ZIP14, with a noteworthy increase in binding percentage observed in the fibrosis group following ZnCl2 treatment, but not in the sham group." (PMID 38221603, 2024).
head and neck cancer (1 paper, 2022). A primary or metastatic malignant neoplasm affecting the head and neck. "MTF1 is a biomarker for predicting disease recurrence in advanced head and neck cancer." (PMID 36117848, 2022).
intrahepatic cholangiocarcinoma (1 paper, 2025). A carcinoma that arises from the intrahepatic bile duct epithelium in any site of the intrahepatic biliary tree. "Notably, overexpression of MTF1 has been observed in human intrahepatic cholangiocarcinoma, where it contributes to tumor differentiation, vascular invasion, and poor prognosis." (PMID 40520016, 2025).
leishmaniasis (1 paper, 2024). Infectious disease that is transmitted through the bite of hematophagous female phlebotomine sand flies. "To date, only one study has associated MTF1 to leishmaniasis, where knock-down of MTF1 increases L. V. panamensis survival in THP-1 monocytes exposed to pentavalent antimonial drugs." (PMID 39028711, 2024).
lymph node metastasis (1 paper, 2024). "No noteworthy association of MTF1 polymorphisms with stage and lymph node metastasis of LC patients was found." (PMID 38943058, 2024).
Menkes disease (1 paper, 2017). A usually severe multisystemic disorder of copper metabolism, characterized by progressive neurodegeneration and marked connective tissue anomalies as well as typical sparse abnormal steely hair. "Cu supplementation and MTF-1 overexpression enhanced pupal survival to the adult stage, and based on this later finding, the authors suggested that induction of MTF-1 expression could be used as an additional approach for the treatment of Menkes disease." (PMID 28684721, 2017).
neuroblastoma (1 paper, 2011). Neuroblastoma (NB) is the most common solid, extracranial childhood tumor. "In IMR-32 human neuroblastoma cells, cadmium has been shown to induce MT-1 expression independent of MTF-1 and zinc." (PMID 21811500, 2011).
nonalcoholic fatty liver disease (1 paper, 2024). "The results revealed significant correlations between dihydrolipoamide s-acetyltransferase (DLAT), dialectical behavior therapy (DBT), metal regulatory transcription factor 1 (MTF1), nonalcoholic fatty liver disease (NFE2L2), and developmental language disorder (DLD)." (PMID 38673957, 2024).
Pain (1 paper, 2022). An unpleasant sensory and emotional experience associated with actual or potential tissue damage, or described in terms of such damage. "MTF1 (metal regulatory transcription factor 1) responds sensitively to both metal excess and deficiency, protects cells from oxidative and hypoxic stresses, is dysregulated in cancer and pain disease." (PMID 36620594, 2022).
pulmonary hypertension (1 paper, 2026). Increased pressure within the pulmonary circulation due to lung or heart disorder. "Pulmonary hypertension (PH) is driven by pulmonary vascular remodeling, in which the zinc-sensing transcription factor metal-responsive transcription factor 1 (MTF-1) may play a pivotal regulatory role." (PMID 41522357, 2026).
rhabdomyosarcoma (1 paper, 2025). A rare aggressive malignant mesenchymal neoplasm arising from skeletal muscle. "This study aimed to investigate the impact of zinc status on human rhabdomyosarcoma (RD) cells and elucidate the involvement of the metal-regulatory transcription factor 1 (MTF1)-Notch1-PI3K/AKT-p21 axis in zinc depletion-induced cell death." (PMID 40970066, 2025).
synucleinopathies (1 paper, 2011). "Therefore, MTF-1 could potentially have beneficial effect in synucleinopathies." (PMID 21386983, 2011).
tumor (59 papers, 2013 to 2026). "Loss of MTF1 significantly reduces cell viability and tumor growth in response to platinum-based drugs cisplatin, and this inhibition can be reversed by expressing heavy metal response genes encoding for MT1A and MT2A." (PMID 39920630, 2025). "Loss of MTF-1 expression has inhibited tumor development by increasing matrix collagen deposition and decreasing vascular density." (PMID 40520016, 2025). "By employing bioinformatics algorithms and immunofluorescence assays, we analyzed the associations between MTF1 and immune infiltration in the tumor microenvironment as well as the expression levels of immune-related molecules." (PMID 39308676, 2024). "Single-cell sequencing revealed that MTF1 was implicated in several tumor development-associated processes, including DNA repair, angiogenesis, and cell invasion." (PMID 38918694, 2024). "In the GPL570 dataset, upregulation of LIPT1, FDX1, LIAS, DLAT, DLD, and PDHB was noted in tumor samples, while MTF1 was downregulated." (PMID 40410601, 2025). "In HCC, reduced m6A modification of MTF1 mediated by METTL3 acetylation leads to enhanced MTF1 expression, thereby promoting cell proliferation and tumor progression." (PMID 39229278, 2024). "Along with the correlations between MTF1 expression and immune-associated molecules, including immune stimulators, immune inhibitors, chemokines, and MHCs, we suggested that MTF1 may be predictive of the tumor immune microenvironment and immunotherapy efficacy in a variety of cancers." (PMID 39308676, 2024). "We investigated the genetic alteration and methylation levels of MTF1 between the primary tumor and normal tissues." (PMID 37380924, 2023). "The TIMER2.0 database was used to analyze the MTF1 expression between tumor and normal tissues across TCGA datasets." (PMID 37380924, 2023). "Among them, the expression levels of CDKN2A, GLS and LIPT1 were significantly upregulated whereas the expression levels of DLAT, DLD, FDX1, MTF1 was significantly downregulated in tumor samples." (PMID 37072493, 2023). "The results demonstrated that the expression of MTF1 was down-regulated while the level of CDKN2A was up-regulated in tumor tissues." (PMID 37662947, 2023). "MTF1 was recently identified to be a propellant of tumor proliferation and metastasis in HCC cells and Hep3B-derived xenografts and was regulated by miR-148a-3p." (PMID 36438201, 2022). "The in vivo study revealed slow growth of MTF-1-knockdown and miR-148a-3p-overexpressing Hep3B-derived xenografts, with reduced tumor volume and weight compared with the control group." (PMID 34660270, 2021). "MTF-1-knockdown and miR-148a-3p-overexpressing Hep3B-derived xenografts showed a slower growth rate, with reduced tumor volume and weight compared with the control group." (PMID 34660270, 2021). "Expression of MTF-1, a transcription factor for MT biosynthesis, was also lower in tumor compared with peri-cancer tissues (11.76 ± 3.52 versus 34.56 ± 12.56)." (PMID 23947958, 2013). "Future strategies may involve combining MTF1 inhibitors with cuproptosis and ferroptosis inducers or stratifying patients according to tumor MTF1 status, thereby overcoming drug resistance and improving therapeutic efficacy." (PMID 41505058, 2026). "We also found that inhibition of the MTF1/ZIC2 axis reduced tumor burden." (PMID 40520016, 2025). "Additionally, MTF1 translocate to the nucleus, activating downstream genes and contributing to tumor initiation and progression." (PMID 40520016, 2025). "The inhibitory effect of MTF1 on cuproptosis, one of the novel regulatory cell death modes in tumor cells, indicated that MTF1 may be a potential therapeutic target for some refractory cancers in the future." (PMID 39308676, 2024). "Through some experiments, we explored the effect of MTF1 knockdown on cuproptosis in tumor cells." (PMID 39308676, 2024).
tumor (continued). "Considering that MTF1 can reduce a cell’s sensitivity to cuproptosis, it is plausible that higher zinc concentrations could protect tumor cells from cuproptosis." (PMID 38918694, 2024). "Meanwhile, the correlations between MTF1 and immune cell infiltration and the expression of immune-related molecules in the tumor microenvironment suggested that MTF1 might play a role in immune regulation and immunotherapy response prediction in some cancers." (PMID 39308676, 2024). "In the last part of this study, we performed a series of experiments and demonstrated that the reduction of MTF1 could increase the sensitivity of tumor cells to cuproptosis." (PMID 39308676, 2024). "Through the analysis of HPA database, we could find that the protein levels of MTF1 in the normal kidney, testis and colon tissues were higher than that in the corresponding tumor tissues." (PMID 37380924, 2023). "Given some normal tissues could not be obtained from the TIMER2.0 database, we further compared the MTF1 expression levels between tumor tissues and normal tissues by GEPIA2.0 that comprises the GTEx datasets." (PMID 37380924, 2023). "MTF1 inhibits matrix collagen deposition and stimulates angiogenesis to promote tumor growth." (PMID 36386799, 2022). "Additionally, increased mRNA level of CDKN2A, DLAT, GLS, LIPT1, and MTF1 in tumor were observed compared to normal group." (PMID 36703728, 2022). "Notably, stable MTF-1-knockdown or miR-148a-3p-overexpressing Hep3B-derived xenografts grew at a slower rate with reduced tumor volume and weight than the control group." (PMID 34660270, 2021). "Furthermore the enrichment of other transcription factors from the same cluster (BATF, PLXNC1, MTF1) as NFkB have been shown to upregulate in other cancers suggesting NFkB to exert and a pro-tumor effect." (PMID 33177572, 2020). "However, some cuproptosis-associated genes, including MTF1, GLS, and CDKN2A, were positively associated with immune, stromal, and ESTIMATE scores, and the levels of immune and stromal cells were high across cancers, with low tumor purity." (PMID 36105090, 2022). "Exosomes enriched with hsa_circ_0000563, an oncogenic circRNA, facilitated tumor growth by binding miR-148a-3p and regulating MTF-1 (metal-regulatory transcription factor-1)." (PMID 41445747, 2025). "Inhibition of the MTF1/ZIC2 signaling axis arrests stem cell formation, thereby preventing the survival of cadmium-transformed cells and inhibiting tumor growth in xenograft models." (PMID 40520016, 2025). "The control vector-transfected CTBPH1 cells exhibited aggressive growth, while the MTF1 knockdown and ZIC2 CRISPR/cas9 knockout cells significantly inhibited tumor growth and reduced tumor weight." (PMID 40520016, 2025). "However, the role of MTF1 in pan-cancer and tumor immunity remains unclear." (PMID 39308676, 2024). "Conversely, genes like CDKN2A, GLS, MTF1, and SLC31A1 exhibited marked upregulation in the tumor, suggesting distinct roles in the pathophysiology of the disease." (PMID 38898987, 2024). "Difference analyses showed that 7 of 10 CRGs were dys-regulated in tumor samples compared with those in normal samples, among which LIPT1, PDHA1, GLS and CDKN2A were up-regulated, and FDX1, DLD and MTF1 were down-regulated." (PMID 37333810, 2023). "We found that FDX1, DLD, PDHA1, MTF1, GLS, and CDKN2A showed differential expression levels between normal and tumor tissues." (PMID 37711156, 2023). "Of note, seven out of ten pivotal CRGs, which were identified in Science article, showed significantly altered expression patterns, with CDKN2A exhibited higher and DLAT, DLD, FDX1, LIAS, MTF1, PDHB exhibited lower expression in tumor tissues (P<0.05)." (PMID 37384293, 2023). "Gene expression profiling showed that SLC31A1, LIPT2, CDKN2A, and GCSH expression was increased in tumor tissues, while NFE2L2, NLRP3, ATP7A, DLD, MTF1, and DLST expression was decreased in tumor tissues compared with normal tissues." (PMID 37065485, 2023).